ZBTB18 (zinc finger and BTB domain containing 18)
Diseases named in the same sentence as ZBTB18 in open-access papers (continued):
Sharing a sentence is not in itself a finding about the gene and the disease.
Insulin resistance (1 paper, 2024). Increased resistance towards insulin, that is, diminished effectiveness of insulin in reducing blood glucose levels. "Consistent with our hypothesis, the activation of hepatic FXR effectively offset the NAFLD phenotype and insulin resistance induced by Zbtb18 silencing, suggesting a novel yet essential role for FXR as the mediator of hepatic Zbtb18’s key functions in maintaining glucose and lipid balance." (PMID 38263084, 2024). "Hepatic Zbtb18 knockout promoted NAFLD features like impaired energy expenditure and fatty acid oxidation (FAO), and induced insulin resistance." (PMID 38263084, 2024). "Consistently, we found that FXR deletion almost completely diminished the Zbtb18-induced beneficial effects on lipid deposition and glucose metabolism dysfunction in vivo and in vitro, coupled with a lack of effects on insulin resistance." (PMID 38263084, 2024).
liver fibrosis (1 paper, 2024). "By contrast, a hepatic Zbtb18 overexpression protected mice against MCD diet induced liver fibrosis, as illustrated by the normal serum ALT and AST levels as compared to littermate control mice." (PMID 38263084, 2024). "Next, we fed Zbtb18LKO mice with MCD diet to prove Zbtb18’s physiological function in the MCD diet induced development of liver fibrosis." (PMID 38263084, 2024). "This key mechanism by which hepatocyte’s Zbtb18 expression alleviates NAFLD and consequent liver fibrosis was further verified by FXR’s deletion and forced expression in mice and cultured mouse primary hepatocytes (MPHs)." (PMID 38263084, 2024). "Moreover, the Zbtb18/FXR axis-stimulated CLTC protein expression remarkably inhibits NLRP3 inflammasome’s activity and alleviated liver inflammatory infiltrations and liver fibrosis." (PMID 38263084, 2024).
lung carcinoma (1 paper, 2021). "Similarly, in lung cancer, the circRNAs, namely, hsa_circ_0051620| SLC1A5 and hsa_circ_0066954| POLQ, are upregulated and are shown to interact with and regulate driver genes, namely, ADAM17, CDH2, RUNX2, and ZBTB18, through miR-338-3p." (PMID 34055888, 2021).
Obesity (1 paper, 2024). Accumulation of substantial excess body fat. "We found that hepatic Zbtb18 deletion easily predisposed the mice to obesity after a lengthy HFD exposure, as illustrated by their higher body weight and fat mass." (PMID 38263084, 2024).
prostate carcinoma (1 paper, 2017). A carcinoma that arises from epithelial cells of the prostate gland. "Moreover, 8 of these TFs (FOXJ2, GATA6, NFE2L1, NFIL3, PRRX2, TEF, EBF2 and ZBTB18) were found to be differentially expressed in this study making them not only candidate biomarkers of prostate cancer but also potential therapeutic targets." (PMID 28380430, 2017).
sensorineural hearing loss (1 paper, 2024). "Among 20 TFs, Zbtb18 participated in sensorineural hearing loss (SNHL), Insm1, Foxo4, Tcf4, and Glis3 were involved in controlling the differentiation of IHCs and OHCs." (PMID 38015350, 2024).
steatosis (1 paper, 2024). Increased lipid within the cytoplasm of cells. "Hepatic Zbtb18 deletion severely hinders FAO in the liver while dramatically suppressing the genes involved in FAO, resulting in a conspicuous hepato-steatosis." (PMID 38263084, 2024).
tumor (9 papers, 2012 to 2025). "The role of Zbtb18 in these diseases is not well understood, but recent findings have shown that it may act as a tumor suppressor gene such that its loss may directly contribute to the development or progression of the disease." (PMID 33608456, 2021). "Here, we show that a novel interaction between the co-activator/co-repressor CTBP and the tumor suppressor ZBTB18 regulates the expression of SREBP genes." (PMID 36414381, 2023). "We show that the tumor suppressor ZBTB18 interacts with the co-factors CTBP1/2 and represses the expression of SREBP genes, involved in de novo lipogenesis." (PMID 36414381, 2023). "Previously, we have identified ZBTB18 as tumor suppressor, which is low expressed in GBM and GBM cell lines." (PMID 36414381, 2023). "Others and we have shown that ZBTB18 functions as a transcriptional repressor of mesenchymal genes and impairs tumor formation." (PMID 36414381, 2023). "Furthermore, rescued assays revealed that the reduced tumor-promoting effect on HCC cells induced by knockdown of circTP63 can be reversed by miR-155-5p inhibitor or ZBTB18 overexpression." (PMID 33685441, 2021). "Overall, these data identify CTBP1/2 as new ZBTB18 interactors in GBM cells and suggest that ZBTB18 might employ both a CTBP-dependent and a CTBP-independent mechanism to repress target genes and mediate its tumor suppressor functions." (PMID 36414381, 2023).
cancer (4 papers, 2021 to 2024). A tumor composed of atypical neoplastic, often pleomorphic cells that invade other tissues. "However, the underlying mechanism of ZBTB18 downregulation in other cancer types also remains undefined." (PMID 33685441, 2021). "Furthermore, a number of Zbtb18 mutants identified in cancer patients showed loss of suppressor activity, which was also accompanied by impaired regulation of PI3K genes." (PMID 33608456, 2021). "Here, we have identified a new role of ZBTB18, CTBP, and LSD1 in the regulation of fatty acid synthesis, which is considered a hallmark of cancer, including GBM." (PMID 36414381, 2023). "Moreover, microglia conditioned with medium from ZBTB18 expressing cells showed a strong reduction of S100A4, a small calcium binding protein that is associated with poor prognosis in various cancers, and which has been linked to EMT and GBM mesenchymal transition." (PMID 39516530, 2024). "ZBTB18 is a member of the Broad complex or poxvirus and zinc finger (BTB/POZ-ZF) protein family, which contains several proteins involved in development and/or cancer formation." (PMID 39516530, 2024).
neurodevelopmental disorder (2 papers, 2017 to 2023). A behavioral and cognitive disorder with onset during the developmental period that involves impaired or aberrant development of intellectual, motor, or social functions. "Four of the 18 high confidence variants (in ERF, SETD1A, SHANK3 and ZBTB18) were recurrent, with these variants having been reported previously in individuals with neurodevelopmental disorders." (PMID 36117209, 2023). "For example, Zbtb18, correlated with resting potential here, is required for normal glutamatergic cell development and has recently been implicated in human neurodevelopmental disorders through genome sequencing." (PMID 29069078, 2017).
cardiovascular disease (1 paper, 2021). "Therefore, evidence about gene polymorphisms associated with cardiovascular disease in the population study can be parallel evidence, at least partially, to support our postulated mechanism linking ZBTB18 to cardiovascular disease via IDs, particularly ID2, ID3, and ID4." (PMID 34440357, 2021). "Little is known about the mechanism linking the ZBTB18 gene to cardiovascular disease among adults." (PMID 34440357, 2021).
ZBTB18 also shares sentences with these, for which no sentence is quoted: autism (2 papers); genetic disorder (2); Silver-Russell syndrome (2); acute lymphoblastic leukemia (1); Huntington disease (1); hypoparathyroidism-retardation-dysmorphism syndrome (1); lymph node metastasis (1); Macrocephaly (1); medulloblastoma (1); schizophrenia (1); speech disorder (1); thyroid cancer (1); thyroid disease (1).